HIF1A (hypoxia inducible factor 1 subunit alpha)
Diseases named in the same sentence as HIF1A in open-access papers (continued):
Sharing a sentence is not in itself a finding about the gene and the disease.
gastric cancer (continued). "In gastric cancer HER-2, EGFR, Akt, HIF-1α and other proteins—all linked to HSP90—appear to be potential targets." (PMID 36966394, 2023). "Existing literature has reported a certain correlation between PLOD2 and HIF1A in gastric cancer and endometrial carcinoma." (PMID 38008826, 2023). "Accordingly, the risk of peritoneal invasion and liver and lymph node metastasis was significantly high, and the 5-year survival rate was significantly low in gastric cancer patients with HIF-1α expressing tumors." (PMID 36846589, 2023). "Of the various roles of HIF-1α in gastric cancer, we opted to focus on its function in cell cycle regulation and the apoptosis pathways." (PMID 38140111, 2023). "To elucidate the role of HIF-1α in gastric cancer cell proliferation, we selected the MKN45 cell line, which exhibited HIF-1α expression under normoxia." (PMID 38140111, 2023). "In gastric cancer,45the high expression of HIF‐1a is related to poor prognosis, and the main mechanism is that HIF‐1α can upregulate FASN activity and then activate SREBP‐1C." (PMID 36994237, 2023). "Studies have revealed that this effect can be achieved in gastric cancer cells by regulating HIF1A expression through IGF2BP3 binding to a specific m6A site on HIF1A mRNA." (PMID 38053093, 2023). "All these findings pointed out the significance of HIF-1α in stem cell-driven metastasis in gastric cancer." (PMID 36846589, 2023). "On the other hand, hypoxia and HIF-1α have prominent roles in the progression of both Lauren types of gastric cancer." (PMID 36846589, 2023). "In diffuse-type gastric cancer cells, HIF-1α is substantially involved in the EMT, which is crucial for the development and progression of diffuse-type gastric tumors." (PMID 36846589, 2023). "Consistent with the relative sparsity of studies in gastric cancer compared with other immensely studied cancers, the number of studies that dissect the role of hypoxia and HIF-1α in chemoresistance is relatively low in gastric cancer." (PMID 36846589, 2023). "The role of HIF-1α in gastric cancer cell growth was markedly elucidated by the results of this study." (PMID 38140111, 2023). "Despite that, the understanding of HIF-1α induced signaling in gastric cancer is far from complete, and the development of efficacious HIF-1α inhibitors bears various challenges." (PMID 36846589, 2023). "Future studies should focus on translating these pre-clinical findings to clinical settings to enable the tangible benefits of the novel targeting of HIF-1α to be translated to patients with gastric cancer." (PMID 38140111, 2023). "MiR-210 mediated HIF-1α-induced EMT to drive invasion of gastric cancer by regulating homeobox 49 expression." (PMID 36714464, 2023). "Confocal fluorescence microscopy was used to examine the expression levels of PD-L1 and HIF-1α in gastric cancer cells in different groups." (PMID 37993847, 2023). "The western blot results indicated a significant reduction in the levels of HIF-1α in gastric cancer cells upon treatment with TH-302 and TH-302 NPs." (PMID 37993847, 2023). "Hypoxia-inducible factor 1 subunit alpha (HIF1A) negatively correlates with miR-20b levels in gastric cancer." (PMID 36717861, 2023). "Overall, our findings highlight the potential of HIF-1α as a viable therapeutic target in gastric cancer." (PMID 38140111, 2023). "Overall, these findings confirm that the downregulation of HIF-1α in gastric cancer cells decreases cell growth and proliferation by inducing cell cycle arrest and increasing apoptotic cell death via the upregulation of the MAPK signaling pathway." (PMID 38140111, 2023). "Selected clinical trials registered to ClinicalTrials.gov testing HIF-1α inhibitors in gastric cancer." (PMID 36846589, 2023). "Understanding the molecular mechanisms by which HIF-1α induces stemness and chemoresistance is essential to prevent tumor progression and chemoresistance in gastric cancer." (PMID 36846589, 2023).
gastric cancer (continued). "HIF1A, the gene encoding HIF-1α protein, is expressed in all the EBV-positive gastric cancer cell lines we have examined to date." (PMID 36980731, 2023). "Here, we screened several of these different classes of HIF-1α-stabilizing drugs for preferential killing of EBV-positive AGS-Akata gastric cancer cells relative to their matched EBV-negative AGS cells." (PMID 36980731, 2023). "In vitro experiments showed that treatment with TH-302 NPs under hypoxic conditions significantly reduced the expression of PD-L1 and HIF-1α in gastric cancer cells." (PMID 37993847, 2023). "The results of Huang’s study indicate that the combination of dextran sulfate and the HIF-1α inhibitor inhibits gastric cancer development more effectively than each drug alone via inhibiting the expression of HIF-1α and N-cadherin." (PMID 37239383, 2023). "The expression of HIF-1α is highly correlated with malignant phenotype and decreased survival in gastric cancer, like several other cancers." (PMID 36846589, 2023). "Mechanistically, the m6A modification of LHPP mRNA by METTL14 represses its expression; LHPP inhibits the phosphorylation of GSK3b through acetylation and mediates HIF1A to inhibit glycolysis, proliferation, invasion and metastasis of gastric cancer cells." (PMID 35568711, 2022). "A previous study in gastric cancer cells showed that Omeprazole treatment reduces HIF-1α expression." (PMID 35563731, 2022). "In the hypoxic environment formed by gastric cancer cells, hypoxia-inducible factor-1α (HIF-1α) can also regulate the transcription of a large number of hypoxia-related genes including multidrug resistance genes." (PMID 36187789, 2022). "Expression of HIF1A is enhanced in gastric cancer cells, and that of HIF1A is highest in drug-resistant gastric cancer cells." (PMID 35659268, 2022). "The over-expression of HIF-1α was positively correlated with tumor infiltration depth, MVD and VEGF expression in gastric cancer, and patients with HIF-1α (+)/VEGF (+) had a relatively poor prognosis." (PMID 35846998, 2022). "Unexpectedly, we did not observe any significant direct interaction between EDDM3A and HIF-1, suggesting that HIF-1α is indirectly involved in the role of EDDM3A in gastric cancer cells." (PMID 35039478, 2022). "High expression of HDAC1 in gastric cancer tissues promotes glycolysis due to an increase in the activity of HIF-1α." (PMID 36438836, 2022). "circMAT2B is a competitive endogenous RNA (ceRNA) that sponges miR-515-5p and increases HIF-1α expression, thereby enhancing glycolysis in gastric cancer cells." (PMID 36438836, 2022). "Meanwhile, other studies affirmed that miR-138 can affect the proliferation, apoptosis, and invasion of lung, ovarian, and gastric cancer cells by targeting the expression of PD-L1, HIF-1α, SOX4, or H2AX." (PMID 35505294, 2022). "Baicalein, another major component of Scutellaria baicalensis, can inhibit glycolysis in gastric cancer cells through the PTEN/Akt/HIF-1α signaling pathway." (PMID 36438836, 2022). "Under hypoxic conditions, activated RON binds to HIF1a and translocates to the nucleus of gastric cancer cells where it can activate c-JUN transcription directly at the promoter locus." (PMID 35454943, 2022). "The oncogene, Never in mitosis gene A-related kinase 2 (NK2), promotes glycolysis in gastric cancer cells by activating the Akt/HIF-1α signaling axis." (PMID 36438836, 2022). "Oleanolic acid inhibited gastric cancer glycolysis by down-regulating the expression of HIF-1α, and celastrol inhibited the expression of GLUT1, HK2, and LDH, thereby inhibiting glycolysis in gastric cancer cells." (PMID 36438836, 2022). "Hypoxia-induced HIF-1α promotes gastric cancer cell proliferation, invasion, and migration both in vitro and in vivo." (PMID 35342404, 2022). "Piezo1 has been shown to induce HIF-1α expression in gastric cancer cells through calcium influx in response to mechanical force." (PMID 34831037, 2021).
gastric cancer (continued). "In gastric cancer, ZEB2-AS1 can heighten the level of HIF-1α by obstructing the activity of miR-143-5p, provoking the invasion of gastric cancer cells." (PMID 34298879, 2021). "Researchs show that epithelial-mesenchymal transition (EMT) playing essential role in modulating gastric cancer metastasis, and the expression of hypoxia inducible factor-1α (HIF-1α) can promote EMT in tumor cells." (PMID 33976746, 2021). "In line with this, the expression of HIF-1α was mediated in an ERK-dependent way under hypoxia in H2O2-treated gastric cancer cells." (PMID 33542787, 2021). "In gastric cancer, resveratrol suppresses the HIF-1α/Hh signaling axis, reversing hypoxia-driven cell invasion and the EMT process." (PMID 34575983, 2021). "miR-224 is up-regulated by hypoxia and HIF-1α, thereby inducing gastric cancer (GC) cell growth, migration and invasion." (PMID 33819917, 2021). "A recent study reported that downregulated HIF-1α inhibited the proliferation of gastric cancer cells." (PMID 33542787, 2021). "Several studies conducted on gastric cancer cells using different approaches (i.e., ChIP assay, luciferase assay, as well as qRT-PCR) revealed the direct relationship between HIF-1α and different miRNAs." (PMID 33673376, 2021). "Then, modulated by AKT, β-catenin and HIF-1α signaling pathways, IL32 was closely associated with metastasis of gastric cancer." (PMID 34116604, 2021). "For example, in gastric cancer, high expression of gastrin increases HIF-1α/VEGF expression and promotes tumour angiogenesis." (PMID 34349170, 2021). "AKIP1 promotes cell invasion and stemness via activating HIF-1α and β-catenin signaling pathways in gastric cancer under hypoxia condition." (PMID 35355804, 2021). "The HIF-1α signaling pathway mediates the promotion of CThrC1 in the migration and invasion of gastric cancer cells." (PMID 34497636, 2021). "Further, HIF-1α knockdown increased ROS production in different gastric cancer cell lines under hypoxia." (PMID 33542787, 2021). "This study has discovered a new mechanism for NPRA to promote gastric cancer development and a new regulatory mechanism for HIF-1α." (PMID 34671022, 2021). "Most recently, SETD1A overexpression was also found in HIF1α-related gastric cancer, enhancing glycolysis and promoting gastric cancer progression." (PMID 34201935, 2021). "Under hypoxia, N-acetylcysteine treatment can significantly decrease the expression of HIF-1α by diminishing ROS, suppressing the survival and invasion ability of gastric cancer cells under hypoxia." (PMID 33542787, 2021). "For example, in gastric cancer cells, PPIs have been shown to inhibit the expression and nuclear translocation of hypoxia-inducible factor 1 α (HIF-1α), Wnt/β-catenin signaling, and the IL-6/STAT3 signaling pathway." (PMID 34262645, 2021). "As for the roles of HIF-1α and β-catenin pathways, they are both involved in tumorigenesis, which includes the pathology of gastric cancer." (PMID 35355804, 2021). "Further, it was noted that wogonin downmodulates HIF-1α levels under normoxia in gastric cancer cells." (PMID 34575983, 2021). "Angiopoietin-like-4 (ANGPTL4), a secreted protein essential for tumor growth and resistance to anoikis in gastric cancer cells, is also upregulated by HIF-1α." (PMID 32780245, 2020). "TGM2 has been shown to be related to hypoxia and HIF1α in malignant pleural mesothelioma and gastric cancer." (PMID 32765489, 2020). "Although the expression of VEGF is up-regulated during hypoxia by HIF-1α, the significant correlation between their IHC stainings is still controversial in previous human studies of gastric cancer, non-small cell lung cancer, and esophageal carcinoma." (PMID 32375802, 2020).
gastric cancer (continued). "Specifically, HIF-1α up-regulates P4HB expression in gastric cancer and together they cooperate to promote GC invasion and metastases." (PMID 32500033, 2020). "HIF-1α has been proven to participate in the pathogenesis of gastric cancer through interactions with various pathways." (PMID 31904088, 2020). "HIF-1α plays an important role in gastric cancer progression and development as a key transcription factor and its overexpression in gastric cancer." (PMID 32963532, 2020). "The level of HIF-1α was significantly increased in GC peritonea with PM, suggesting that the metastatic peritoneal microenvironment in gastric cancer is indeed hypoxic." (PMID 33081836, 2020). "miR-186 regulates the expression of hypoxia inducible factor 1α (HIF-1α) and blocks aerobic glycolysis in gastric cancer cell lines." (PMID 32083000, 2020). "In gastric cancer cells, hypoxia (1% O2)-enhanced HIF1α stabilization coincides with the downregulation of CAV1 expression and epithelial–mesenchymal transition." (PMID 32825247, 2020). "Overexpressed HIF-1α is a critical factor in the acceleration of malignant behaviors in gastric cancer, such as angiogenesis, invasion, metastasis and apoptosis." (PMID 31904088, 2020). "Overexpressed HIF-1α accelerates malignant behaviors in gastric cancer including angiogenesis, invasion, metastasis, and apoptosis." (PMID 32076440, 2020). "Gastric cancer cell lines with PVT1 overexpression show increased HIF-1α mRNA and protein levels, that are reduced with a miR-186 mimic." (PMID 32083000, 2020). "Further, we show that BHLHE40 selects its targets by cooperation with other transcription factors that regulate the expression, and the function, of BHLHE40, such as HIF1α in gastric cancer and in HCC." (PMID 32577154, 2020). "Inhibition of HIF-1α expression by dextran sulfate reduces gastric cancer peritoneal metastasis acting through decreased integrin β1 expression." (PMID 32780245, 2020). "It has further been shown that silencing PVT1 can reduce the expression of HIF-1α and enhance the sensitivity of gastric cancer cells to DDP." (PMID 32460771, 2020). "Taken together, data from our study suggest that PKM2 knockdown impeded cell migration, invasion, and EMT of gastric carcinoma cells via the HIF-1α/BCL-6 pathway." (PMID 33376737, 2020). "The downregulation of miR-186 and its connection with Twist1 and HIF-1α has been recognized as antitumor growth biomarker in gastric cancer." (PMID 32099601, 2019). "There was a was statistically significant (X2=4.395, P=0.037) difference in HIF-1α expression between lymph node metastasis tissues and gastric cancer tissues." (PMID 33817155, 2019). "An earlier study showed that the interaction between HIF-1α and β‐catenin contributes to migration of hypoxic gastric cancer cells." (PMID 31085796, 2019). "In gastric cancer tissues, there was a statistically significant different between the expression of HIF-1α and Snail, HIF-1α and Twist, NDRG2 and Snail, and NDRG2 and Twist." (PMID 33817155, 2019). "Baicalein reversed hypoxia-induced 5-FU resistance in gastric cancer cells through suppression of glycolysis via regulation of the PTEN/Akt/HIF-1α signaling pathway." (PMID 29898734, 2018). "The different effect of EGFR or HIF-1α mRNA in breast, ovarian, lung, and gastric cancer was also demonstrated by the Kaplan-Meier Plotter algorithm, which documents the different tissue-specific prognostic effect of both markers." (PMID 30513863, 2018). "Expression of HIF-1α mRNA in tumor tissues and adjacent healthy tissues of 58 gastric cancer patients was detected by qRT-PCR." (PMID 29899167, 2018). "Our data have shown that HIF-1α has important functions in the development and progression of gastric cancer." (PMID 29899167, 2018). "In the present study, expression level of HIF-1α was found to be significantly higher in tumor tissues than in adjacent healthy tissues in 52 out of 58 gastric cancer patients." (PMID 29899167, 2018).
gastric cancer (continued). "Overall survival of gastric cancer patients with high expression level of HIF-1α was significantly shorter than that of patients with low expression level of HIF-1α (P<0.05)." (PMID 29899167, 2018). "ROC curve analysis showed that the area under curve (AUC) of serum HIF-1α in the diagnosis of gastric cancer was 0.9068 with 95% confidence interval of 0.8482–0.9653 (P<0.001)." (PMID 29899167, 2018). "Serum levels of HIF-1α protein were significantly higher in gastric cancer patients than in normal healthy people." (PMID 29899167, 2018). "Expression of HIF-1α in tumor tissues and adjacent healthy tissues as well as serum collected from both gastric cancer patients and normal healthy controls was detected by qRT-PCR." (PMID 29899167, 2018). "Expression of HIF-1α was significantly higher in tumor tissues than in adjacent healthy tissues in most gastric cancer patients." (PMID 29899167, 2018). "HIF-1α also has been proved to participate in the pathogenesis of gastric cancer through interactions with various pathways." (PMID 29899167, 2018). "Our findings and previous studies show that up-regulation of HIF-1α is highly likely to be involved in the pathogenesis of gastric cancer." (PMID 29899167, 2018). "HIF-1α siRNA silencing inhibited the proliferation, migration, and invasion of gastric cancer cells, while PI3K activator sc3036 treatment reduced those inhibitory effects." (PMID 29899167, 2018). "ELISA was used to measure levels of HIF-1α protein in serum of gastric cancer patients and normal healthy people." (PMID 29899167, 2018). "So we conclude that down-regulation of HIF-1α can possibly inhibit the proliferation, migration, and invasion of gastric cancer by inhibiting PI3K/AKT pathway and VEGF expression." (PMID 29899167, 2018). "Cell proliferation, migration, and invasion abilities of two gastric cancer cell lines with HIF-1α siRNA silencing were significantly increased after sc-3036 treatment, but were still significantly lower than those of control cells (untransfected cells)." (PMID 29899167, 2018). "Kaplan–Meier method was used to draw survival curves to evaluate the prognostic value of serum HIF-1α for gastric cancer." (PMID 29899167, 2018). "In the present study, HIF-1α siRNA silencing significantly reduced the expression level of VEGF in two gastric cancer cell lines (P<0.05)." (PMID 29899167, 2018). "Expression of HIF-1α was significantly down-regulated in tumor tissues than in adjacent healthy tissues in most gastric cancer patients." (PMID 29899167, 2018). "Down-regulation of HIF-1α can inhibit the proliferation, migration, and invasion of gastric cancer possibly by inhibiting PI3K/AKT pathway and VEGF expression." (PMID 29899167, 2018). "In the present study, expression of HIF-1α in tumor tissues and adjacent healthy tissues as well as serum collected from both gastric cancer patients and normal healthy people was detected." (PMID 29899167, 2018). "Transcriptome analysis of four high EBV+ primary gastric cancers from the TCGA cohort indicated that HIF-1α mRNA was, on average, 2.9-fold more abundant than HIF-2α mRNA (range 1.9-fold to 4.9-fold), with HIF-3α mRNA undetectable above background level." (PMID 28617871, 2017). "As such, activation of HIF-1α is considered a key step that favors malignant disease progression, also in gastric cancer." (PMID 28401064, 2017). "It has been reported that TFF3 regulates the expression of VEGF and HIF-1α induced by hypoxia, in gastric cancer cell lines." (PMID 29100347, 2017). "The present study was designed to investigate the effects and the mechanism underlying these effects of K5 on both HIF-1α-induced angiogenesis and GRP78-dependent apoptosis resistance in gastric cancer cells." (PMID 29072683, 2017). "We strongly believe that H. pylori oncogenic CagA induces ROS production to stabilize HIF-1α and influences gastric cancer initiation and progression." (PMID 29108235, 2017).